IL6 (interleukin 6)
Diseases named in the same sentence as IL6 in open-access papers (continued):
Sharing a sentence is not in itself a finding about the gene and the disease.
Insulin resistance (continued). "On the other hand, pro-inflammatory molecules such as visfatin and interleukin-6 (IL-6) are known to contribute to insulin resistance, unbalanced fat metabolism, oxidative stress, and systemic inflammation." (PMID 41280712, 2025). "Obese patients have elevated levels of inflammatory factors such as interleukin-6, which can induce insulin resistance." (PMID 40568559, 2025). "Key inflammatory markers like IL-6 and TNF-α, central to PCOS pathophysiology and linked to insulin resistance, were significantly reduced by BL21, indicating its regulatory effect on inflammation and sex hormone balance." (PMID 39898662, 2025). "Butyrate reduces inflammatory factors (such as TNF-α and IL-6) in adipose tissue and improves insulin resistance by inhibiting the NF-kB pathway." (PMID 40950607, 2025). "MetS originates from energy imbalance, genetic/epigenetic, and lifestyle factors, mediated through free fatty acid-induced insulin resistance, IL-6/TNF-α-mediated inflammation, and fetuin-A-driven mitochondrial reactive oxygen species dysregulation." (PMID 40703156, 2025). "The observed stress hyperglycemia in Cluster 1 suggests enhanced gluconeogenesis and glycogenolysis, potentially driven by insulin resistance and counter-regulatory hormones such as catecholamines, cortisol, and pro-inflammatory cytokines (e.g., IL-6, TNF-α)." (PMID 40745510, 2025). "Under obese conditions, a shift toward pro-inflammatory M1 macrophage polarization occurs, accompanied by increased production of cytokines such as TNF-α and IL-6, both of which disrupt insulin signaling and contribute to insulin resistance." (PMID 40869401, 2025). "It was also found that IL-6 promotes insulin resistance, stimulates gluconeogenesis, and hepatic secretion of triglycerides." (PMID 41527594, 2025). "Chronic low-grade inflammation, characterized by elevated cytokines like IL-6 and TNF-α, is a hallmark of hyperlipidemia and insulin resistance." (PMID 40509408, 2025). "Other proinflammatory cytokines implicated in the impairment of insulin signaling leading to insulin resistance in the liver and adipose include IL-1β and IL-6." (PMID 40985048, 2025). "Despite this effect, theories have been proposed stipulating that IL-6 leads to peripheral insulin resistance; the role of IL-6 in T1DM has been more researched compared to the effect on T2DM." (PMID 40149994, 2025). "Inflammatory cytokines such as TNF-α, IL-1β, and IL-6 activate multiple signaling pathways, leading to insulin resistance, impaired insulin secretion, and promotion of diabetes and its complications." (PMID 41306290, 2025). "Increased pro-inflammatory cytokines such as TNF-α and IL-6, along with adiponectin, have been shown to contribute to endothelial dysfunction, oxidative stress, and insulin resistance." (PMID 40076485, 2025). "Studies demonstrate that IL-6 secreted by WAT can induce insulin resistance through different mechanisms, including the activation of inflammatory proteins in the liver and impairment of insulin signaling in fat cells." (PMID 40647244, 2025). "These cytokines, including TNF-α, IL-1β, and IL-6, not only exacerbate periodontal tissue destruction but also promote insulin resistance." (PMID 41019448, 2025). "VAT is metabolically active and by secreting free fatty acids and adipokines such as leptin, TNF-α, and IL-6 contributes to fostering systemic inflammation, endothelial dysfunction, and insulin resistance." (PMID 41141356, 2025). "M1 MΦs secrete pro-inflammatory cytokines, such as tumor necrosis factor-alpha (TNF-α), interleukin-6 (IL-6), and interleukin-1 beta (IL-1β), which impair insulin signaling in adipocytes and contribute to insulin resistance." (PMID 41602577, 2025). "For instance, IL-6 concentrations are significantly higher in obese individuals and show a positive correlation with homeostatic model assessment of insulin resistance." (PMID 41226411, 2025).
Insulin resistance (continued). "Some fundamental studies have indicated that insulin resistance is closely associated with an increase in the release of inflammatory factors, such as TNF-α and IL-6." (PMID 40936909, 2025). "Higher CRF is linked to improved mitochondrial efficiency, enhanced glucose uptake, and reduced hepatic insulin resistance through the release of myokines including interleukin-6, which are known to have anti-inflammatory and insulin-sensitizing effects." (PMID 41276872, 2025). "Prior human studies in MASLD have shown increased baseline IL-6, IL-17A and TGF-β1 which are associated with hepatic inflammation, insulin resistance, and fibrosis." (PMID 40869413, 2025). "Bariatric surgery reduces visceral adiposity, which is strongly associated with insulin resistance, and leads to decreased secretion of pro-inflammatory cytokines like tumor necrosis factor-alpha (TNF-α) and interleukin-6 (IL-6)." (PMID 40626220, 2025). "For instance, IL-6’s dual role in promoting insulin resistance and regulating energy homeostasis highlights its potential as a therapeutic target." (PMID 40519917, 2025). "Adipose tissue, particularly when in excess, secretes pro-inflammatory adipokines (e.g., TNF-α, IL-6) and reduces adiponectin levels, contributing to systemic insulin resistance and hepatic steatosis." (PMID 41476919, 2025). "Persistent immune activation in RA leads to excessive production of pro-inflammatory cytokines such as TNF-α, IL-6, and IL-1β, which contribute to hepatic insulin resistance and lipid accumulation." (PMID 40797381, 2025). "IL-6 is a strong predictor of lipid disorders and insulin resistance, suggesting diverse mechanisms through which this cytokine influences metabolic disturbances." (PMID 40137151, 2025). "Elevated levels of IL-6 in serum, liver, and adipose tissue in patients with MASH have been linked to insulin resistance, steatosis, and liver injury." (PMID 40668532, 2025). "IMAT was measured via calf muscle MRI, and body composition (BMI, fat mass index), metabolic markers (hs‐CRP, TNF‐α, IL‐6, insulin resistance), and circulating cell‐free mitochondrial DNA (ccf‐mtDNA) were assessed." (PMID 40635410, 2025). "Interleukins such as IL-1β, IL-6, and IL-10 emerge as central mediators in β-cell dysfunction, chronic inflammation, insulin resistance, and the progression of diabetes-related complications." (PMID 40804870, 2025). "These invading immune cells secrete several pro-inflammatory cytokines like TNF-α, IL-6, and IL-1β that assist in the development of insulin resistance along with other metabolic dysfunctions." (PMID 40218884, 2025). "IL-6 plays a significant mediating role in the inflammatory pathways associated with PCOS, especially in patients with insulin resistance." (PMID 40226143, 2025). "Inflammatory pathways and oxidative stress—driven by NADPH oxidase activation and proinflammatory cytokines such as TNF‐α and IL‐6—also contribute to insulin resistance by inducing serine phosphorylation of IRS‐1 and impairing insulin receptor activity." (PMID 41143273, 2025). "Given the known inhibitory effects of inflammatory cytokines such as IL-6 and TNFα on insulin signaling, these findings suggest that SerpinA3k expression contributes to insulin resistance through proinflammatory mechanisms." (PMID 41329353, 2025). "Lean diabetics exhibited distinct biochemical features - higher adiponectin but elevated CRP and IL-6 - supporting inflammation and β-cell dysfunction as key drivers over insulin resistance." (PMID 41523554, 2025). "Suppression of TNF-α and IL-6 levels restores a more normal inflammatory response, hence inhibiting the inflammatory condition that induces insulin resistance." (PMID 40218884, 2025). "These pro-inflammatory cytokines, particularly TNF-α and IL-6, can lead to insulin resistance in adipose tissue, skeletal muscle, and the liver by disrupting insulin signaling." (PMID 40689212, 2025).
Insulin resistance (continued). "The pro-inflammatory cytokine IL-6 contributes to insulin resistance through serine/threonine phosphorylation of IRS-1, thereby disrupting insulin signal transduction." (PMID 40959695, 2025). "The role of IL-6 in insulin resistance remains controversial, although elevated levels of IL-6 have been linked to the development of type 2 diabetes." (PMID 41227378, 2025). "Dysregulation of IL‐6 production is linked to the pathogenesis of T2DM, insulin resistance and inflammation." (PMID 39355932, 2025). "This imbalance is associated with systemic inflammation and insulin resistance, evidenced by elevated levels of C-reactive protein (CRP), interleukin-6 (IL-6), tumor necrosis factor-alpha (TNF-α), and lipopolysaccharide-binding protein (LBP)." (PMID 40308637, 2025). "This study aims to evaluate the relationship between IL-6 concentrations and the severity of insulin resistance in patients with PCOS and to assess the potential of IL-6 as a diagnostic biomarker for insulin resistance within these patients." (PMID 40226143, 2025). "IL-6 was reported to induce insulin resistance by inhibiting transcription or reducing phosphorylation of insulin receptor substrate-1, while elevated hsCRP was a prestigious biomarker in inflammation and associated tightly with cardiovascular risk." (PMID 38954305, 2025). "Meanwhile, hyperglycemia also induces the release of inflammatory mediators such as interleukin-6 (IL-6), which worsens insulin resistance and contributes to systemic inflammation." (PMID 41268458, 2025). "IL-6 plays a critical role in metabolic and vascular functions, significantly contributing to the development of insulin resistance, type 2 diabetes, and atherosclerosis." (PMID 40699839, 2025). "Metabolic correlations with total lipids, triglycerides, low-density lipids, and fasting glucose and insulin suggested IL-6's role in insulin resistance." (PMID 40226143, 2025). "Concurrently, HGK deficiency in T cells induces the degradation of TRAF2, elevating IL-6 levels, which promotes Th17 differentiation and leads to insulin resistance." (PMID 40096134, 2025). "Pro-inflammatory chemokines and cytokines, such as MCP-1, TNF-α, and IL-6, can induce insulin resistance through various mechanisms, including inflammation promotion and impairment of insulin sensitivity." (PMID 40286055, 2025). "In fact, elevated levels of TNF-α were reported in DM patients and IL-6 was considered to mediate adverse metabolic effects and contribute to insulin resistance." (PMID 40230621, 2025). "Increased concentrations of pro-inflammatory cytokines, including tumor necrosis factor-alpha (TNF-α), interleukin-6 (IL-6), and C-reactive protein (CRP), are implicated in the development of insulin resistance and the deterioration of pulmonary function." (PMID 40142617, 2025). "It is frequently associated with systemic inflammation, characterized by elevated levels of TNF-α and IL-6, and metabolic dysregulation, including insulin resistance." (PMID 40093012, 2025). "Elevated levels of inflammatory cytokines such as tumor necrosis factor α, interleukin 6, and C-reactive protein, commonly associated with FRAILTY and insulin resistance, have been implicated in DR pathogenesis." (PMID 40778361, 2025). "First, VAT is highly proinflammatory, producing adipokines such as leptin, TNF-α, and IL-6, which promote endothelial dysfunction, inflammation, and insulin resistance." (PMID 41141356, 2025). "While IL-6 regulates the immune response triggered by pro-inflammatory cytokines, it can also be considered an indicator of metabolic stress, insulin resistance, and endothelial dysfunction." (PMID 40005437, 2025). "Visceral adipose tissue promotes systemic inflammation through the secretion of tumor necrosis factor-α, interleukin-6, and other proinflammatory cytokines, which subsequently lead to insulin resistance and altered hepatic lipid metabolism." (PMID 41438141, 2025).
Insulin resistance (continued). "Exercise reduces the levels of pro‐inflammatory biomarkers such as C‐reactive protein (CRP), interleukin‐6 (IL‐6) and tumour necrosis factor‐alpha (TNF‐α), which are associated with insulin resistance and cardiovascular diseases." (PMID 40371883, 2025). "These indicate that DTG and RAL reduce LPL levels through two mechanisms: a direct effect on LPL expression and an indirect effect by inducing insulin resistance through increased levels of the inflammatory cytokine such as IL-6." (PMID 41156460, 2025). "There is a positive correlation between insulin resistance and inflammatory markers, such as CRP and IL-6, suggesting that prediabetes increases the risk of developing cerebrovascular events." (PMID 41296388, 2025). "A proinflammatory cytokine cascade, including interleukin-6, tumor necrosis factor-alpha, and Interleukin-1 beta, disrupts insulin signaling pathways and leads to insulin resistance." (PMID 40725663, 2025). "Inflammation in adipose tissue is mediated by the secretion of pro-inflammatory cytokines such as tumor necrosis factor-alpha (TNF-α) and interleukin-6 (IL-6), which can impair insulin signaling and promote insulin resistance." (PMID 40672421, 2025). "TNF can activate STAT3, HIF-1a, Th17, and IL-6, while IL-1 can induce insulin resistance, HIF-1 production, and JAK-STAT signals." (PMID 39891057, 2025). "IL‐6 triggers insulin resistance by disrupting insulin signaling and glucose transport, primarily through downregulation of IRS‐1 and GLUT‐4." (PMID 40551726, 2025). "This activation leads to the secretion of pro-inflammatory cytokines, such as TNF-α and IL-6, which increase insulin resistance in GDM." (PMID 40724491, 2025). "This comprehensive analysis highlights IL-6's significant association with PCOS symptoms, metabolic imbalances, and insulin resistance, underscoring its potential role in the pathophysiology of PCOS." (PMID 40226143, 2025). "The current study extends previous research on IL-6’s role in liver steatosis and insulin resistance by highlighting its deleterious impact on the pancreas, particularly in modulating β-islet cells’ health and immune cell composition." (PMID 40693271, 2025). "Increased pro-inflammatory cytokines, such as TNFα, IL-6, and adiponectin, have been shown to contribute to endothelial dysfunction, oxidative stress, and insulin resistance." (PMID 40243674, 2025). "IL-6, IL-11, OSM, and LIF enhance acute-phase liver responses, cause insulin resistance in liver cells, and drive macrophages to a pro-inflammatory M1 state, thus worsening liver inflammation." (PMID 40969371, 2025). "Analysis of the relationship between IL-6 levels and insulin resistance revealed a moderate positive correlation, with a linear model (R2=0.56) explaining 56% of the variation in IL-6 levels as HOMA-IR increased." (PMID 40226143, 2025). "These metabolic effects have been linked to increased oxidative stress, insulin resistance, and enhanced production of proinflammatory mediators such as TNF-α, IL-6, and CRP." (PMID 40724965, 2025). "Excessive lipid storage predisposes individuals to insulin resistance, as large dysfunctional adipocytes exhibit reduced insulin sensitivity and secrete pro-inflammatory cytokines (e.g., TNF-α, IL-6), further exacerbating metabolic dysregulation." (PMID 40218884, 2025). "The study also evaluated IL-6's predictive ability for insulin resistance using receiver operating characteristic (ROC) curve analysis, calculating the area under the curve (AUC), with a significance threshold set at p<0.05." (PMID 40226143, 2025). "The levels of blood glucose, lipids, insulin resistance (IR), Interleukin-6 (IL-6), interleukin-1β (IL-1β), tumor necrosis factor-α (TNF-α) were detected, and the pancreatic tissue damage was evaluated by Hematoxylin and eosin (H&E) staining microscope." (PMID 41098781, 2025). "When compared to TNF-α, IL-6 exhibits broader systemic effects, impacting both insulin resistance and ovarian physiology." (PMID 40385768, 2025).
Insulin resistance (continued). "Collectively, our data indicate that TSH activates inflammatory signaling and promotes the secretion of IL-1α, IL-1β and IL-6 in macrophages, thus aggravating insulin resistance." (PMID 40523992, 2025). "Pro-inflammatory cytokines such as TNF-α, IL-1β, and IL-6 produced by macrophages contribute to insulin resistance and inflammation in diabetes." (PMID 41472730, 2025). "Pathways linked to TNF-α and IL-6/JAK/STAT3 signaling are well-established contributors to adipose inflammation and systemic insulin resistance." (PMID 41148235, 2025). "Chronic low-grade inflammation, driven by adipose tissue macrophage infiltration and pro-inflammatory cytokines such as tumor necrosis factor (TNF)-α and interleukin (IL)-6, exacerbates insulin resistance." (PMID 41348748, 2025). "It is widely recognized that adipose tissue macrophages release tumor necrosis factor-α (TNF-α) and interleukin-6 (IL-6), which are involved in the development of insulin resistance." (PMID 40943118, 2025). "Overeating causes the accumulation of liver fats that contribute to the production of most adipokines, such as leptin, resistin, adiponectin, tumor necrosis factor-alpha (TNF-alpha), and IL-6, which are involved in inducing insulin resistance and inflammation." (PMID 41441034, 2025). "Visceral fat also releases pro-inflammatory molecules like TNF-α and IL-6, which interfere with insulin signaling and worsen insulin resistance." (PMID 40612313, 2025). "Excess visceral adipose tissue aggravates this situation by releasing adipokines (e.g., TNF-α, IL-6) that worsen insulin resistance and foster vascular damage." (PMID 40149704, 2025). "TNF-α and IL-6 are key pro-inflammatory cytokines that are consistently elevated in insulin resistance and GDM." (PMID 40722699, 2025). "As an upstream target of FOXO4, IL6/STAT3 signaling activation promotes insulin resistance in adipose tissue and muscle, and JAK2/STAT3 activation induces insulin resistance in HepG2 cells." (PMID 41573199, 2025). "Elevated TNF-α and IL-6, central to hepatic inflammation and systemic insulin resistance, are potential targets for anti-cytokine therapies currently evaluated in metabolic disease." (PMID 41220583, 2025). "TNF, and interleukin-6 (IL-6) have been shown to disrupt insulin signaling, reducing glucose uptake and contributing to insulin resistance." (PMID 40453076, 2025). "Other relevant cytokines include Interleukin-6 (IL-6) and Interleukin-1 beta (IL1β), which promote insulin resistance by interfering with insulin signaling in peripheral tissues." (PMID 41304906, 2025). "These MΦs secrete pro-inflammatory cytokines such as TNF-α, IL-6, and IL-1β, which inhibit insulin signaling in adipocytes and promote insulin resistance." (PMID 41602577, 2025). "NaP plays a role in regulating insulin resistance, mitochondrial function, and the production of IL-1β, IL-6, and IL-17 in T2DM." (PMID 40636075, 2025). "Cytokines such as TNF-α and IL-6, released during trauma, exacerbate insulin resistance, further aggravating hyperglycemia." (PMID 40343929, 2025). "Pro-inflammatory cytokines such as tumor necrosis factor-alpha (TNF-α) and interleukin-6 (IL-6) contribute to insulin resistance and vascular dysfunction, further complicating glucose metabolism." (PMID 40076938, 2025). "Proinflammatory cytokines such as tumor necrosis factor-α (TNF-α), interleukin-6, and galectin-3, induce insulin resistance." (PMID 41374008, 2025). "In fact, it has been reported that IL‐10 prevents diet‐induced insulin resistance both in liver and skeletal muscle, through a reduction in the production of tissue IL‐6 and TNF‐α." (PMID 40207597, 2025). "This process upregulates pro-inflammatory cytokines, such as tumor necrosis factor-alpha (TNF-α) and interleukin-6 (IL-6), contributing to endothelial dysfunction and insulin resistance." (PMID 41002774, 2025).